BRAF (B-Raf proto-oncogene, serine/threonine kinase)
Diseases named in the same sentence as BRAF in open-access papers (continued):
Sharing a sentence is not in itself a finding about the gene and the disease.
tumor (continued). "In subgroups like KRAS or BRAF, which have demonstrated higher response rates to ICIs treatment, combining TKI with immunotherapy could potentially enhance therapeutic synergy, modulating the tumor microenvironment." (PMID 39859299, 2025). "While tumours lacking variants in these genes but also BRAF/RAS and NF1 have been dubbed ‘quadruple wild-type’, it is more appropriate to specify those genes that have been tested, e.g. WT for KIT, PDGFRA, NF1 and BRAF/RAS." (PMID 38840030, 2025). "Several goals of care discussions were conducted while the tumour was considered BRAF-negative." (PMID 41562808, 2025). "Of note, only one of all 24 tumor samples with genomic MAPK alteration and none of the five BRAF V600E mutated tumors had been treated with MAPK directed targeted agents before surgery, which excludes an extrinsic therapy induced reduction of pERK levels in these cases." (PMID 40251387, 2025). "Considering the growing body of evidence demonstrating excellent response of BRAF/MEK inhibitors in tumors with this mutation, the decision to initiate therapy with dabrafenib/trametinib rather than to pursue radiotherapy (RT) was made by the tumor board." (PMID 39634188, 2024). "However, we observed that activated AKT level underwent a decrease followed by a rebound in BRAF-mutant CRC cell RKO and gradually increased in wild-type CRC cell Caco2, which might impair the anti-tumor effect of SHP2 inhibitor." (PMID 39014007, 2024). "However, this combination is not approved for the treatment of patients with tumors harboring BRAF fusions as type I RAF inhibitors are ineffective in this setting and may paradoxically enhance tumor growth." (PMID 38291372, 2024). "In the group with RAIR metastatic TC, BRAF levels were positive in four patients despite the negative status of the primary tumor tissue, which may reflect tumor heterogeneity or the development of a new clone of cells responsible for disease progression." (PMID 39336882, 2024). "Moreover, no sufficient information on molecular tumor traits (microsatellite instability and BRAF status) was available for pathogenicity clarification." (PMID 38843250, 2024). "Moreover, although we report the coexistence of BRAF and NRAS mutations within the same tumor, this does not necessarily imply these mutations can co-occur within single cells, as each tumor cell has its transcriptional repertoire that dictates its fate." (PMID 38396984, 2024). "Except for UTE3, a primary tumor cell line characterized by a low TMB, the other four cell lines all harbored one or two alterations each in genes related to the RAS/MAPK pathway (i.e., the target of avutometinib) including a KRAS G13C alteration in UTE1 and a BRAF D594N alteration in UTE2." (PMID 39240189, 2024). "Therefore, pathologically activated BRAF/MAPK signaling, possibly by BRAFV600E, initiates and promotes tumor development through transcriptionally elevating USP15 and protecting TBX3 from degradation, in addition to direct transcriptionally up-regulating TBX315." (PMID 38750011, 2024). "Tumors with BRAF V600E mutations had significantly lower TMB scores (4.6 mut/Mb) compared to other BRAF alterations and driver gene negative tumors (≥10.2 mut/Mb) yet had a significantly higher frequency of high PD-L1 scores (46%) than the other tumor groups (≤28%)." (PMID 39664186, 2024). "Of note, the sensitivity of cell-free DNA assays at identifying and quantitating copy-number alterations can be low if there is low amount of tumor DNA present; in our case, the high VAFs of BRAF present suggest that lack of identification of MET amplification was not a false negative." (PMID 39626159, 2024). "Moreover, CRP showed prognostic value for survival irrespective of tumour location and BRAF/KRAS status." (PMID 38613909, 2024).
tumor (continued). "In mice, mutant BRAF-induced ERK activation is cancer stage-dependent with significantly higher levels of phosphorylated ERK in high-grade dysplasia and carcinoma, suggesting that different tumor stages may require different levels of p-ERK." (PMID 38921956, 2024). "In mice, mutant BRAF-induced ERK activation is cancer stage-dependent with significantly higher levels of phosphorylated ERK in high-grade dysplasia and carcinoma 3, suggesting that different tumor stages may require different levels of p-ERK." (PMID 36778401, 2024). "Notably, the tumor-agnostic approval of dabrafenib (a BRAF inhibitor) in combination with trametinib (a MEK inhibitor) for BRAF V600E–mutant cancers explicitly excludes CRCs due to known intrinsic resistance." (PMID 38938274, 2024). "Notably, ARAF has a significantly lower kinase activity than BRAF and CRAF, but its overexpression prolonged the duration of MAPK activation, potentially creating conditions conducive to tumor cell survival and the transcription of neuroendocrine markers in the presence of EGFR-TKIs." (PMID 39456595, 2024). "In addition, the same group showed that miR-224 expression is lower in stage IV BRAF-mutated and dMMR tumors, an effect we also observed in MSI-H/EMAST-H tumors, irrespective of the tumor stage." (PMID 39202367, 2024). "However, this study was limited by the lack of histopathological verification of the FNAB results in some patients and the absence of data on BRAF status in tumor tissue." (PMID 39336882, 2024). "For patients with RAS and BRAF wild-type, especially those with primary tumors located in the left colon or rectum, cetuximab has demonstrated superiority over bevacizumab in terms of early tumor shrinkage (ETS), depth of tumor response (DPR), disease control rate (DCR), and overall survival (OS)." (PMID 39109286, 2024). "However, this combination is not recommended for the treatment of patients with tumors harboring BRAF fusions as type I RAF inhibitors are ineffective in this setting and may paradoxically enhance tumor growth." (PMID 38779936, 2024). "Moreover, an important caveat of the BRAF inhibitors monotherapies is the paradoxical activation of the MAPK pathway, according to which, a RASmut background contraindicates the administration of BRAF inhibitors due to tumor potentiation." (PMID 38254847, 2024). "Median PFS was comparable between panitumumab and bevacizumab for RAS/BRAF WT and MSS/MSI-L patients but tended to be shorter with panitumumab than bevacizumab in patients with a RAS/BRAF mutation and/or MSI-H, regardless of tumor sidedness." (PMID 38347302, 2024). "MSI analysis is not recommended as it may be less sensitive than IHC in ECs especially for the detection of MSH6 deficiency, and BRAF c.1799T>A variants are rare and do not discriminate between LS and sporadic MMR deficient tumours." (PMID 38962168, 2024). "The average BRAF mRNA expression was significantly higher in premenopausal patients, patients with high tumor grade, hormone receptor–negative status, and non-luminal tumors compared to postmenopausal patients, patients with low-grade, hormone receptor–positive, and luminal disease." (PMID 38919805, 2024). "ICB is, however, considered inefficacious for the majority of patients presenting MSS/MMR-proficient CRC, which causes low tumour antigenicity and unlike the majority of metastatic microsatellite-instable/MMR-deficient CRC cases, often co-exists with high RAS/BRAF-driven oncogenic activity." (PMID 38664577, 2024). "However, a pooled analysis of two trials evaluating the combined biomarkers of KRAS, NRAS, BRAF, and PIK3CA showed a significantly reduced benefit from anti-EGFR therapy in patients with any mutant tumor compared with patients with all wt tumors (interaction tests P < 0.05 for PFS, OS, and ORR)." (PMID 37974093, 2023).
tumor (continued). "These include the combination of BRAF inhibitors with MEK inhibitors to block multiple signaling pathways, the use of EGFR inhibitors in combination with BRAF inhibitors, and the combination of targeted therapies with immunotherapy to enhance the immune response against tumor cells." (PMID 37444584, 2023). "However, these two anti-EGFRs are only active when the tumor cells of the patient do not present mutations at the level of the RAS, PIK3CA and BRAF genes." (PMID 37176143, 2023). "The combination of crizotinib with the ERBBi afatinib demonstrated synergistic cytotoxic effects, significantly reducing 2D and 3D invasion, migration and colony formation independent of BRAF/NRAS mutation status, and resulting in decreased tumour volume in vivo." (PMID 37181747, 2023). "On the other hand, BRAF V600E mutation did not predict RLN invasion in PTC ≤ 1 cm, and we reckon that the very characteristic of the tumor itself may have much significant impacts on the probability of RLN invasion." (PMID 36651705, 2023). "Tumours without BRAFV600E mutation can be characterized further to identify alternative druggable genetic alterations of MAPK signaling pathway (e.g., FGFR1 missense mutation, BRAF fusion)." (PMID 36831464, 2023). "Recently, we and others have described single cases or small studies of tumours with concomitant alterations of H3-K27M and mitogen-activated protein kinase (MAPK) pathway showing a possible longer survival compared to patients with DMG H3 K27-altered, BRAF and FGFR1 wild-type." (PMID 38066305, 2023). "According to the Canadian Consensus Practice Guidelines on tumour biomarker testing for mCRC, the minimum biomarker testing required across all Canadian jurisdictions for mCRC patients requires testing for KRAS/NRAS, BRAF, and MMR/MSI prior to the initiation of 1L therapy." (PMID 37754511, 2023). "Finally, we explored the combination of MAPK inhibitors, TVB-3664 and arsenic trioxide (ATO, as a clinically used ROS-inducer) in Mel006 BRAF mutant PDX as a gold model of therapy resistance and assessed the effect on tumor growth, survival and systemic toxicity." (PMID 37072838, 2023). "At a median follow-up of 2 years, median PFS was superior with combination ipilimumab–nivolumab compared with ipilimumab monotherapy for both BRAF wild-type and mutant tumours (not reached vs. 4.4 months, HR 0.40, and 8.5 vs. 2.7 months, HR 0.38, respectively)." (PMID 37404764, 2023). "Pronounced tumour inflammation also led to BRAF-negative prediction." (PMID 37570213, 2023). "Notably, the similar allele frequencies of the BRAF and KRAS mutations suggested their co-existence in the same cancer cells and not a clonal evolution of tumor cells exclusively with KRAS mutation." (PMID 36967525, 2023). "New research will focus on improving target therapies, such as new BRAF/MEK inhibitors, using FGFR inhibitors, Raf inhibitors, or a combination of multiple therapies, in relapsing rare glial and/or neuronal tumours after surgery or surgically inaccessible tumours." (PMID 36831464, 2023). "Moreover, BRAFi significantly decreased the expression of HIF‐1α in D4M tumors, and the effect was maintained in combination with anti‐m‐VEGFA treatment but not after anti‐mVEGFA alone, indicating that BRAF inhibition is critical for abrogating tumor hypoxia." (PMID 37183363, 2023). "To address this question, we analysed BRAF copy number variation (CNV) by digital droplet Polymerase Chain Reaction (ddPCR) on genomic DNA from one BRAFV600E H3.3-K27M tumour (case #2) and from a H3.3-K27M BRAFWT clone derived from this primary tumour in vitro (online resource)." (PMID 38066305, 2023). "Since innate immune cells can contribute to tumor suppression boosting a strong adaptive immune response, we hypothesized that infiltration on M1 macrophages in the TME by BRAF/VEGFA targeting would enhance the efficacy of the ICB, which primarily unleashes anticancer T‐cell response." (PMID 37183363, 2023).
tumor (continued). "The ongoing randomized PARERE study, investigating rechallenge with panitumumab followed by regorafenib versus the reverse sequence in chemorefractory RAS/BRAF wt patients selected by liquid biopsy, could further clarify the role of anti-EGFR according to primary tumor site." (PMID 36895480, 2023). "It has been shown that vemurafenib or apatinib could significantly inhibit tumor growth in NSCLC patients with BRAF V600E mutantion who did not respond to conventional chemotherapy regimens." (PMID 36759818, 2023). "Previous studies have identified incomplete tumor “capsule” as an imaging marker for predicting MVI, postoperative extrahepatic metastasis, and high BRAF and RAF1 expression in HCC, and the latter could accelerate tumor proliferation and differentiation and promote tumor invasion and metastasis." (PMID 37191923, 2023). "In tumour without BRAFV600E mutation, extensive screening is valuable to identify an alternative druggable genetic alteration of the MAPK pathway (e.g., gene fusion involving BRAF, RAF1, ALK, ROS1)." (PMID 36831464, 2023). "First, in patients with BRAF V600E WT SKCM, compared with the ICD-low group, the ICD-high group had significantly more immune-enhanced cell infiltration, immune-activated signaling pathway aggregation, tumor microenvironment effects, and a better clinical prognosis." (PMID 36704723, 2023). "Furthermore, the oncogenic contexts were qualitatively different from each other: loss of tumor suppressors generally led to increased rates of tumor initiation and growth in the KRAS backgrounds, had more muted effects in the BRAF context, and had variable effects in the EGFR context." (PMID 37828026, 2023). "In addition, short-term treatment could slow the growth of 4/5 BRAF mutant human PDXs to some extent, including one PDX model that was generated from a BRAF-inhibitor-resistant tumor." (PMID 35385746, 2022). "In summary, copy number variations and a tumor size > 5 mm could predict high-risk PTC with LN metastasis risk, whereas BRAF mutation showed no prediction value for LN metastases." (PMID 36313748, 2022). "Therefore, the addition of anti-PD-1/PD-L1 to BRAF and MEK targeted therapy could help prevent tumor progression." (PMID 36844955, 2022). "Our research provided intensive study of the pathway of the BRAF V600E‐mERK‐GSK‐3β pathway regulating mPTP, and has thus identified a new selective target for anti‐tumour drugs that may restore the death threshold of tumour cells." (PMID 35748101, 2022). "Furthermore, lipid β-oxidation and mitochondrial OxPhos were crucial for tumor repopulation of regressed pancreatic tumors in vivo; for in vivo age-related resistance to BRAF/MEK inhibition of melanoma; and for anoikis resistance and tumor progression in ovarian cancer." (PMID 35356277, 2022). "Due to the complexity of the tumor microenvironment (TME) and a lack of a rational mechanistic basis, it is urgent to investigate the immune infiltration and identify prognostic biomarkers in BRAF mutated SKCM patients." (PMID 36531226, 2022). "Different patients may develop drug-addicted cells at different rates and removing drug for patients without sufficient BRAF amplification to promote drug addiction may instead promote tumor growth." (PMID 36418460, 2022). "Notably, seven patients (18.9%) did not experience tumor progression during 2L treatment with BRAF ± MEKi and in four of them treatment was still ongoing at the time of data-lock." (PMID 35565212, 2022). "Thirty-seven patients presented with an MSI-H and BRAF c.1799T > A (p.V600E)-negative tumour." (PMID 35954501, 2022). "Mutations in RAS or BRAF did not affect OS, however, we did find that the few patients with RAS/BRAF wild-type cancers showed a worse RFS (P = 0.006) and a significantly increased tumor load (PCI score, P = 0.031)." (PMID 35927254, 2022).
tumor (continued). "Of note, atorvastatin marginally reduced tumour number in this model, but did not completely abrogate the tumours, in stark contrast to the BRAF model, suggesting that the inhibitory effects of atorvastatin could in part depend on the timing of the treatment." (PMID 34779486, 2022). "BRAF/MEK inhibitor monotherapies also paradoxically increase the risk of aberrant MAPK pathway signaling in nonmelanoma cells, increasing the rates of RAS-mutant tumor reactivation and secondary cancer development (e.g., cutaneous squamous-cell carcinoma)." (PMID 35453572, 2022). "The sample size of each tumor type varied from 36 (CHOL) to 1,084 (BRCA), and the cancer types with a small sample size might not reflect the general spectrum of BRAF mutation status." (PMID 35910024, 2022). "Six patients (16.7%) presented with tumor recurrence after a mean of 35 ​± ​29 months; 2 were treated with TCA, 1 with EEA, 1 with photon radiation therapy, and another with proton therapy followed by chemotherapy with BRAF/MEK pathway inhibitors for multiple disseminations through the CSF." (PMID 36248121, 2022). "However, neither the genes encoding AURKA and USP8 nor those encoding USP48, BRAF, BRG1 and CABLES were affected in this tumor." (PMID 35563252, 2022). "A recent study showed targeting DDR1 as a therapeutic strategy against resistance to BRAF and MEK inhibitors, further confirming the significance of our findings, which suggest an unprecedented role of the interactome of DDR1, BCR, and ABL1 proteins with EGFR-ERBB2-4 signaling in tumor progression." (PMID 35664781, 2022). "However, the BRAF expression did not correlate with gender (p=0.2), tumor size (p=0.07), and tumor focality (p=0.09)." (PMID 35646190, 2022). "However, this does not agree with growing literature on KRAS and BRAF mutant tumors demonstrating rather it is the mitigation of ROS that benefits tumor growth in this context." (PMID 36253360, 2022). "This difference in glutamine levels was reflected in the tumor epigenetic landscape, with an increase in H3K27 methylation driven by low glutamine in the core of the tumor leading to an increase in expression of dedifferentiation markers and an increased resistance to BRAF inhibitor treatment." (PMID 36203456, 2022). "In addition, it was shown that tumor immune infiltration and control could be improved by short-term blockage of MEK and BRAF, together with anti-PD-1/L1 Abs, in a CD8-T cells-dependent way." (PMID 35628540, 2022). "The observation from preclinical and translational data that the effect of BRAF and MEK inhibitors on the tumour microenvironment is dynamic and temporally dependent raises the possibility that sequential administration of BRAF/MEKi and CPI could optimise anti-tumour immunogenicity." (PMID 35366166, 2022). "Additionally, BRAFi inhibits tumor growth by inhibiting ERK, which in turn inhibits the negative feedback inhibition of ERK on RAS, partially restoring RAS activity and leading to the formation of BRAF dimers induced by RAS." (PMID 36181568, 2022). "Finally, RET fusions have been found in a small fraction of patients with CRC (<1%), predominantly on the right side, RAS and BRAF wild-type tumours, and carry a worse prognosis compared to patients without RET fusions." (PMID 35207616, 2022). "Interestingly, evDNA detected five additional variants (BRAF L319I, RAD51B T107K) in patients 3, 4, 9 and 10 that were not present in the respective tumor." (PMID 35205822, 2022).